EPB41 (erythrocyte membrane protein band 4.1)
Description:
Protein 4.1 is a major structural element of the erythrocyte membrane skeleton. It plays a key role in regulating membrane physical properties of mechanical stability and deformability by stabilizing spectrin-actin interaction. Recruits DLG1 to membranes. Required for dynein-dynactin complex and NUMA1 recruitment at the mitotic cell cortex during anaphase.
Synonyms: 4.1R; EL1; HE
Tractability: Antibody: its Gene Ontology location is reachable by antibodies, with high confidence; the Human Protein Atlas places it where antibodies can reach. PROTAC: ubiquitination databases record sites on it; its protein half-life has been measured.
Gene: Protein-coding gene on chromosome 1 (28,887,091 to 29,120,046, forward strand). Ensembl gene ENSG00000159023.
Subcellular location: Cytoplasm, cytoskeleton; Cytoplasm, cell cortex; Nucleus
Subcellular location (Human Protein Atlas): Cell Junctions; Plasma membrane; Cytokinetic bridge; Cytosol; Mitotic spindle; Nuclear bodies
Pathways (Reactome):
Neuronal System: Neurexins and neuroligins
Gene Ontology:
Molecular function: 1-phosphatidylinositol binding; phosphoprotein binding; protein binding; structural constituent of cytoskeleton; spectrin binding; actin binding; cytoskeletal protein binding; structural molecule activity
Biological process: positive regulation of protein localization to cell cortex; actin cytoskeleton organization; actomyosin structure organization; regulation of calcium ion transport; regulation of intestinal absorption; response to fluid shear stress; cortical actin cytoskeleton organization
Cellular component: cell cortex; cortical cytoskeleton; cytosol; intercellular bridge; mitotic spindle; plasma membrane; protein-containing complex; basolateral plasma membrane; cytoskeleton; spectrin-associated cytoskeleton; nucleus
Genetic constraint (gnomAD): Loss-of-function variants: 60 observed, 100.84 expected, observed/expected ratio (o/e) 0.59, 90% interval 0.48 to 0.74. The upper end of that interval is the gene's LOEUF score, 0.74, which puts it in group 3 of 6, group 1 being the genes least tolerant of losing a copy. Missense variants: 831 observed, 1,039.2 expected, observed/expected ratio (o/e) 0.8, 90% interval 0.75 to 0.85. Synonymous variants: 328 observed, 362.73 expected, observed/expected ratio (o/e) 0.9, 90% interval 0.82 to 0.99.
Homologues: Orthologues: chimpanzee EPB41 (99% identical), rabbit EPB41 (93% identical), dog EPB41 (92% identical), guinea pig EPB41 (92% identical), pig EPB41 (92% identical), mouse Epb41 (89% identical), macaque EPB41 (88% identical), rat Epb41 (87% identical), tropical clawed frog epb41 (69% identical), zebrafish epb41a (58% identical), Drosophila melanogaster cora (33% identical), Caenorhabditis elegans frm-1 (32% identical), and 5 more. Paralogues in human: EPB41L2 (51% identical), EPB41L3 (48% identical), EPB41L1 (41% identical), EPB41L4B (23% identical), EPB41L5 (22% identical), FRMD5 (20% identical), FRMD3 (20% identical), EPB41L4A (19% identical), FRMD6 (16% identical), MYLIP (13% identical).
Diseases named in the same sentence as EPB41 in open-access papers:
EPB41 is named in the same sentence as 41 diseases in open-access papers, as found by Europe PMC text mining. Sharing a sentence is not in itself a finding about the gene and the disease. The quoted sentences say what the papers report.
elliptocytosis (11 papers, 2007 to 2025). "Most cases of hereditary elliptocytosis result from mutation of the α spectrin gene (SPTA1) or of EPB41 encoding protein 4.1." (PMID 40530495, 2025). "One individual ('HS34') carrying a pathogenic EPB41 mutation was excluded from further analyses, as examination of a peripheral blood smear confirmed the diagnosis of hereditary elliptocytosis." (PMID 35845192, 2021). "Variations in the EPB41 exon cause hereditary elliptocytosis." (PMID 39331630, 2025). "Although EPB41 has been reported to be associated with elliptocytosis, the clinical significance of the EPB41 mutation site chr1:29344739 in the child remains unclear." (PMID 38678261, 2024). "The variants in the gene encoding protein 4.1 (EPB41) and in the specific regions of the spectrin genes cause hereditary elliptocytosis (HE)." (PMID 38069343, 2023).
meningioma (5 papers, 2009 to 2024). A generally slow growing tumor attached to the dura mater. "Many studies have revealed the capacity of EPB41 to predict the prognosis of various cancers and its critical role in the development of tumours, such as breast cancer, meningiomas, prostate cancer, and hepatocellular carcinoma." (PMID 32723333, 2020). "EPB41 has been identified as a tumor suppressor in the molecular pathogenesis of meningiomas." (PMID 34884649, 2021).
prostate carcinoma (5 papers, 2010 to 2021). A carcinoma that arises from epithelial cells of the prostate gland. "Previous studies have suggested changes in the expression of specific components in prostate cancer, especially of 4.1 proteins (encoded by EPB41 genes) which form nodes in this network." (PMID 20860828, 2010). "We observed significant hypermethylation in 4 of the 10 target genes (MAN1A1, EPB41, HSD17B13, and MYOM2) in primary prostate cancer patient tumors (n = 503) compared to normal prostatic samples (n = 50) (p ≤ 0.05)." (PMID 34884649, 2021). "Additionally, Ualcan online database analysis showed increased promoter methylation of both EPB41 and HSD17B13 in prostate cancer patients compared to healthy controls." (PMID 34884649, 2021). "For ETS fusion-negative prostate cancers subtypes, novel gene fusions have also been identified, including SLC45A3:BRAF, ESRP1:RAF1, SLC45A3:BRAF, ESRP1:RAF1, C15orf21:Myc, EPB41:BRAF, and TMEM79:SMG5." (PMID 23957008, 2013).
anaemia (4 papers, 2020 to 2024). "It is noteworthy, therefore, that the EPB41 gene located within a Blanco Orejinegro and Hartón del Valle BTA2 CSS cluster region is associated with resistance to anaemia and trypanotolerance in African cattle." (PMID 38571912, 2024). "In addition, the potentially related diseases to specific patients’ proteins were anemias or hematopoietic system diseases (proteins HBZ, EPB41, HP, PGK1, HBE1, BPGM, and ALDOA)." (PMID 36519745, 2022).
breast carcinoma (3 papers, 2020 to 2024). "Elevated levels of EPB41 expression have been correlated with prolong survival in human breast cancer patients." (PMID 38951817, 2024). "For example, EPB41, PSMA1, LEP, LECT2, and ZNF35 were associated with breast cancer." (PMID 32528533, 2020).
hepatocellular carcinoma (3 papers, 2019 to 2024). A malignant tumor that arises from hepatocytes. "Dysregulation of EPB41 is implicated in hepatocellular carcinoma and lung cancer." (PMID 39020437, 2024).
Sepsis (2 papers, 2017 to 2025). Sepsis is defined as life-threatening organ dysfunction caused by a dysregulated host response to infection. "The correlation matrix highlights strong positive relationships among key genes such as TNFSF10, EPB41, PLVAP, and TMCC2, suggesting their coordinated involvement in sepsis pathogenesis." (PMID 40362669, 2025).
adenoma (1 paper, 2024). A neoplasm arising from the epithelium. "Noteworthy, the numbers of RNA interactors of some MP-RNAs (WDR62, TGFBR3, RN7SL5P, RMRP, MIR663AHG, AJ009632.2, CDKL1, OPRD1, PLOD1, AL117692.1, ATP13A2, EPB41) in cancer tissue were significantly increased compared with that in paracancer and adenoma." (PMID 38773399, 2024).
Azoospermia (1 paper, 2020). Absence of any measurable level of sperm,whereby spermatozoa cannot be observed even after centrifugation of the semen pellet. "EPB41 is one of the pleiotropic monogenic disorder's genes that cause male infertility, and manifests as azoospermia." (PMID 32614449, 2020).
cervical cancer (1 paper, 2022). A primary or metastatic malignant neoplasm involving the cervix. "Increased miR-486-3p represses cells metastasis and proliferation in many tumors including cervical cancer, oral cancer and squamous cell carcinoma, suggesting that circ-EPB41 overexpression also suppressed NSCLC cell metastasis and proliferation via adsorption of miR-486-3p." (PMID 35725615, 2022).
Hodgkins lymphoma (1 paper, 2013). A heterogeneous group of malignant lymphoid neoplasms of B-cell origin characterized histologically by the presence of Hodgkin and Reed-Sternberg (HRS) cells in the vast majority of cases. "We also selected the non-Hodgkin lymphoma B cell line, RL-7, as a hematopoietic cell line amenable to siRNA for analysis of EPB41 splicing in response to RBM38 knockdown." (PMID 24250749, 2013).
keloid (1 paper, 2023). An irregularly shaped, elevated mark on the skin caused by deposits of excessive amounts of collagen during wound healing. "We believe that the decreased expression of EPB41 in keloid-susceptible patients is related to the increase of inflammatory cytokines in early wound healing and the inability to progress to the proliferative stage of healing." (PMID 36777722, 2023). "However, our results are innovative in revealing early wound healing-related genes (EPB41, TPM1, NF2, PARD3) in keloid patients from the perspective of alternative splicing regulated by RBP." (PMID 36777722, 2023).
lymph node metastasis (1 paper, 2022). "However, high expression of circ-EPB41 was positively related to lymph node metastasis (negative vs positive), TNM stage (I/II or III/IV vs high) and tumor size (≤ 3 cm vs > 3 cm)." (PMID 35725615, 2022).
non-small cell lung carcinoma (1 paper, 2021). A group of at least three distinct histological types of lung cancer, including non-small cell squamous cell carcinoma, adenocarcinoma, and large cell carcinoma. "EPB41 suppressed the Wnt/β-catenin signaling in non-small cell lung cancer by sponging ALDOC." (PMID 34456184, 2021).
thalassemia (1 paper, 2024). An inherited blood disorder characterized by a decreased synthesis of one of the polypeptide chains that form hemoglobin. "In our study, we found overexpression of the genes SLC4A1, ANK1, EPB41, EPB42, SPTA1, SPTB, and STOM, all of which are involved in maintaining erythrocyte structure and function, in patients with thalassemia and SCD." (PMID 39519257, 2024).
tumor (17 papers, 2008 to 2024). "EPB41 is closely linked to defects in hair follicle structure and function, as well as skin lesions and tumor development." (PMID 38674368, 2024). "Immunofluorescence detection of OCT-4 staining found that circ-EPB41 silencing suppressed stemness marker OCT-4 expression in tumor tissues." (PMID 35725615, 2022). "We then examined the effect of circ-EPB41 knockdown on tumor formation in a stable lentiviral strain (sh-circEPB41) or in sh-NC A549 cells." (PMID 35725615, 2022). "Western blot detection also found that expression of stemness markers SOX2, OCT-4, Nanog and CD133 was decreased after circ-EPB41 silencing in tumor tissues, suggesting that circ-EPB41 promoted the progression of NSCLC by regulating stemness." (PMID 35725615, 2022). "Given that circ-EPB41 is mainly localized to the cytoplasm, we hypothesized that circ-EPB41 might regulate tumor biological behavior by sponging miRNAs." (PMID 35725615, 2022). "Together, this evidence supports the biological relevance of EPB41 in tumour biology." (PMID 32723333, 2020). "Together, this evidence supports the biological relevance of EPB41 in tumor biology." (PMID 32039036, 2019). "Paradoxically, a group of proteins, including C1QL3, EPB41, SNX10, FGF14, GLB1L2 and TRAK2, have been reported as good prognostic markers or tumor suppressors in the NmFMC group." (PMID 38951817, 2024). "EPB41 suppresses epidermal growth factor receptor (EGFR) activation and thus plays an important role as a tumor suppressor in cancer development." (PMID 37444464, 2023). "Several of the genes described here can be assigned to categories that are involved in the development of solid tumors: MC1R is involved in pigmentation/UV protection, EPB41 and MYCT in tumor suppression, and ADGRG3 in immunomodulation." (PMID 37444464, 2023). "Here, we report that circ-EPB41 is an essential circRNA that is frequently upregulated in NSCLC tissues, and that high expression predicts poor prognosis for lymph node metastasis, high TNM stage and large tumor size." (PMID 35725615, 2022).
cancer (11 papers, 2007 to 2024). A tumor composed of atypical neoplastic, often pleomorphic cells that invade other tissues. "EPB41 encodes the erythrocyte protein band 4.1, which was first identified in erythroid cells but is also expressed on other normal and cancer cell types." (PMID 21261996, 2011). "Their study demonstrated that the inhibition of EPB41 expression in cancer cells increased the levels of ALDOC protein released from the EPB41-ALDOC complex." (PMID 38397451, 2024). "One of the hallmarks of cancer is evasion of immune response, and EPB41, a cytoskeletal protein, has a role in dendritic cell synapse and its role in the immune system involves antigen presentation." (PMID 36386805, 2022). "Erythrocyte membrane protein band 4.1 (EPB41) was one of the interesting targets as it is known to play a role in the invasion of other cancers." (PMID 36386805, 2022). "Mutations in well-known cancer genes located on chromosome 1p, such as NRAS (1p13.2), GADD45A (1p31.2–31.1), CDKN2C (1p32.2), RAD45(1p32) and EPB41 (1p36.2–p34), have so far only sporadically been detected." (PMID 34385566, 2021). "Thus, features such as EPB41, PSMA1, FGFR3, MRAS, and LEP which were involved in cancer-related pathways and with high PPI degrees (>/ = 10) were considered as PRBs for further analysis." (PMID 32528533, 2020). "Furthermore, by screening through the criteria of the PPI network, cancer-related pathway and TRS modeling, essential features with gene symbols of EPB41, PSMA1, FGFR3, MRAS, LEP, C7orf46, LOC285000, LBP, ZNF35, SLC30A3, LECT2, RNF7, and DYNC1I1 were identified as PRBs for COAD patients." (PMID 32528533, 2020).
infection (4 papers, 2013 to 2022). The state of being infected such as from the introduction of a foreign agent such as serum, vaccine, antigenic substance or organism. "EgPSC infection also caused the upregulation of Cgn, Epb41, Cldn8, Shroom3, Cask, Rab3b, Epb41l2, Csnk2b, Prkcb, and MyI12a." (PMID 36713407, 2022).
EPB41 also shares sentences with these, for which no sentence is quoted: hematologic disorder (2 papers); hereditary spherocytosis (2); malaria (2); osteosarcoma (2); acanthocytosis (1); deep vein thrombosis (1); developmental delay (1); diffuse large B-cell lymphoma (1); hemoglobinopathies (1); hereditary anemia (1); histoplasmosis (1); hyperkinetic disorders (1); lung carcinoma (1); male infertility (1); melanism (1); microcephaly (1); neuroblastoma (1); oral cancer (1); small cell lung carcinoma (1); Spherocytosis (1); squamous cell carcinoma (1); teratozoospermia (1); viral infection (1).